CD4 (CD4 molecule)
Diseases named in the same sentence as CD4 in open-access papers (continued):
Sharing a sentence is not in itself a finding about the gene and the disease.
co-infection (continued). "Recent studies show expansion of HLA-DR+ and CD38+ CD4+ T cells in PTB and HIV-TB co-infection." (PMID 30231065, 2018). "High levels of CD4 cell count (over 500 cells/mm3) reduces TB-related mortality among HIV-positive people as well as those not co-infected with TB and therefore it plays an important role in the incidence of HIV/TB co-infection." (PMID 30424736, 2018). "Risk factors for bone disease in HIV‐positive (HIV+) subjects include both classical risk factors for osteoporosis and fracture and factors linked to HIV itself, such as inflammation, reconstitution syndrome, low CD4, ART, and co‐infection with hepatitis B and C viruses." (PMID 30283906, 2018). "In addition, co-infection of HTLV-1-infected cells by HIV-1 is also possible, suggesting the potential presence of both viruses in the same CD4+ T-cells in co-infected individuals." (PMID 29267225, 2017). "We report on the function and phenotype of CD4+CD27-CD28- Treg in PBMC of CMV-infected individuals, with or without HIV co-infection, and compare them to CD4+CD27-CD28- PBMC from CMV-seronegative controls." (PMID 28683106, 2017). "As shown by the Kaplan-Meier survival estimates, the probability of maintaining CD4+ ≥ 350 cells/mm3 was higher for patients without HCV co-infection (d_hcv = 0) rather than for those with co-infection (d_hcv = 1)." (PMID 28166729, 2017). "The early loss of CD4+ T cells in the gastrointestinal tract is a hallmark of HIV/SIV pathogenesis; yet the effect of HPgV/SPgV co-infection on gut CD4+ T cell depletion has never been examined." (PMID 29073258, 2017). "Although monotherapy (mART) effectiveness in maintaining viral suppression and CD4 cell count has been extensively examined in HIV-1-infected patients, its impact on HIV-1 reservoir, immune activation, microbial translocation and co-infection with Epstein-Barr Virus (EBV) is unclear." (PMID 28926641, 2017). "Multivariate regression analyses were employed, adjusting for age, sex, body mass index, smoking, hepatitis C virus co-infection, injection drug use, comorbidities, and HIV status (for all participants), and HIV viral load, CD4+ T-cell counts, and antiretroviral therapy (for HIV+ participants)." (PMID 29097998, 2017). "There may be the need to consider the confounder effects of sex, pre-ART CD4+, and pre-ART HIV-1 viral load in the discourse on HIV and HBV co-infection." (PMID 27251610, 2016). "HIV co-infection reduced the frequency of HCV specific CD4+ T cells with no detectable effect on CD8+ T cells or neutralizing antibody levels." (PMID 27455208, 2016). "To rule out the influence of ART on the relationship between CD4+ T cell counts and M. tb co-infection status, we divided the subjects into ART and without ART subgroups according to the HIV treatment." (PMID 26959228, 2016). "Our finding suggests that CD4+ T-cell counts appear to be a determining factor for active TB rather than M. tb co-infection." (PMID 26959228, 2016). "Hierarchy low CD4+ T-cell counts and Th1 effector function in HIV-1+ individuals are associated with increased frequencies of active TB, but not M. tb co-infection." (PMID 26959228, 2016). "Interestingly the percentages of double negatives CD4 and CD8 splenocytes increased in P. yoelii 17XNL infected groups, and Leishmania co-infection were able to delay this enhancement." (PMID 27446022, 2016). "The observations made in this study indicate that CMV-coinfection may support the expansion of the CD8+ T cell compartment and counter the improvement of the CD4:CD8 ratio." (PMID 27824907, 2016). "There is a tendency, although not statistically significant, towards a better HCV-specific T cell response in patients with CD4 counts >200, suggesting that the lack of CD4+ T cell help in co-infection likely has an impact on HCV specific Immunity." (PMID 27455208, 2016).
co-infection (continued). "Finally, we explored if correlates of immune activation including CD4/CD8 ratio, KT ratio, and Human Pegivirus co-infection predict YFV response among HIV-infected subjects." (PMID 27941965, 2016). "Pre-ART CD4+, pre-ART HIV-1 pVL, and sex may be important in determining ART outcomes in individuals on ART with HIV and HBV co-infections." (PMID 27251610, 2016). "Median VL and CD4+ cell count for the ITT population were similar across treatment groups (overall median of 5.03 log10 copies/mL and 207 cells/mm3, respectively), as was rate of hepatitis B or C co-infection." (PMID 26730818, 2016). "In the present study, we evaluate Malaria/Leishmaniasis disease outcome, Th1/Th2 cytokine levels and the CD4 and CD8 T-cell profiles in a co-infection murine model (BALB/c) of Plasmodium yoelii 17XNL (Py) and Leishmania amazonensis (La) or L. braziliensis (Lb)." (PMID 27446022, 2016). "In this Asian cohort of HIV-infected patients, HCV co-infection, but not HBV co-infection, was associated with lower CD4 cell recovery after ART and increased mortality." (PMID 26933963, 2016). "Given that CD4+ T cells were efficiently depleted in spleen, lung and LN in anti-CD4 mAb-treated animals, we reasoned that this model resembles progression from LTBI to active TB in human HIV/Mtb co-infection." (PMID 27391012, 2016). "In contrast, CD4, CD8 T cells and NK cells were similar to IAV infection, and both coinfection and influenza caused a modest but non-significant reduction in alveolar macrophages (FigEV2C)." (PMID 26265006, 2015). "After 13 months, there was evidence of CD4 recovery in individuals with HCV co-infection and their CD4 count increased per month relative to individuals without HCV (estimate = 3.99, 95% CI [1.48, 6.50] cells/mm3 per month, p = 0.002)." (PMID 26225723, 2015). "The main inclusion criteria were: at least 3 years’ receipt of HAART; current CD4+ count ≥ 500 cells/mm3; undetectable viral load for at least 24 months; no hepatotropic virus co-infection." (PMID 25811634, 2015). "These cells were principally derived from the TCM subset irrespective of pathogen specificity and MTB-specific IFN-γ and IL-2-dual secreting CD4+ cells expressed relatively little CD127 in HIV co-infection and very little PD-1 regardless of HIV infection." (PMID 26417433, 2015). "Programmatic priorities should focus on ensuring all patients with RR-TB/HIV co-infection initiate ART regardless of CD4 count, with special attention for patients with CD4 counts ≤ 100 to initiate ART as soon as possible after RR-TB treatment initiation." (PMID 26555134, 2015). "In Cameroon, CPT is indicated in all cases of TB/HIV co-infection both in adults and children, irrespective of the CD4 cell count level and WHO clinical stage." (PMID 25941570, 2015). "A previous study suggested that HCV-Ab positive patients are more likely to have an incomplete CD4+ restoration, whereas others suggested that previous intravenous drug use, but not HCV co-infection, is associated with suboptimal CD4 response to HAART." (PMID 26020949, 2015). "The variation in the inherent quality of these CD4+ T-cell responses and impact of HIV co-infection may contribute to the timing of co-infectious diseases in HIV infection." (PMID 26417433, 2015). "Well-established factors predicting virological response to PEGIFN/RBV-treatment in HIV/HCV coinfection include HCV GT, HCV-RNA, IL28B, liver fibrosis, insulin resistance, low-density lipoprotein (LDL)-cholesterol-levels, low CD4+ counts and nadirs and y-glutamyltransferase (GGT) levels." (PMID 26599080, 2015). "In contrast, lowering CD4+ T-cell count was recorded in hookworm/HIV co-infection, but the difference was not significant (P = 0.69)." (PMID 26415705, 2015). "The mean gains in CD4 cells at 6 months of follow up periods was 150.5 ± 14.1 cells/mm3 in PLWHs with TB co-infection and 146.7 ± 7.2 cells/mm3 in those without TB co-infection." (PMID 26374623, 2015).
co-infection (continued). "Regarding clinical outcomes, in the initial six months, the intervention group contained higher percentages of patients without co-infections and of patients with CD4+ >500 cells/mm3." (PMID 25889580, 2015). "Our results confirm the need to scale up access to viral hepatitis screening in Cameroon to permit early diagnosis of co-infection in newly diagnosed HIV-patients to allow early initiation of the appropriate ART irrespective of CD4 cell counts." (PMID 26371878, 2015). "In those without HIV co-infection a higher percentage of several EBV-specific CD4+ T-cell subsets expressed PD-1 than CMV-specific cells." (PMID 26417433, 2015). "At six months, the intervention group contained higher percentages of patients without co-infections and of patients with CD4+ >500 cells/mm3." (PMID 25889580, 2015). "The obvious outcome of HTLV-I or HTLV-II and HIV co-infection is an increased CD4+ cells count without any immune benefit for patients." (PMID 24592307, 2014). "In Cameroon, CPT is indicated in all cases of TB/HIV co-infection in both adults and children, irrespective of the CD4 cell count level and WHO clinical stage." (PMID 25506830, 2014). "Genes related to cell cycle arrest were significantly mediated by HIV which may lead to dysfunction of CD4+ T cells and acceleration of HCV-related disease progression in the co-infections." (PMID 24520951, 2014). "There was a mean decrease in plasma HIV level (−0.3 log10 ± 0.83) after successful treatment of helminths, but an increase in HIV load in patients that had no helminth coinfection in parallel with significant reduction in CD4+ T cells." (PMID 24774967, 2014). "For HIV/HCV co-infection, the cell cycle arrest in G2 phase induced by HIV would lead to a depletion of CD4+ T cells, and may partially result in a less efficient in HCV clearance." (PMID 24520951, 2014). "With the onset of PTB co-infection in the dampened immune environment of HIV-1 infected individuals, we observed further significant increase in Foxp3 expression in CD4 T-cells of co-infected individuals in comparison to individuals infected only with HIV-1 but similar CD4 count (<250 cells/μl)." (PMID 25198707, 2014). "Factors independently associated with a greater increase in CD4 counts at 12 months were CDC stage A-B, baseline HIV-RNA <105 copies/mL, absence of HBV/HCV coinfection, pursuit of the same cART during the first year, and initiation of cART after 2004." (PMID 25395106, 2014). "The investigation of co-infection between TB and intestinal helminths suggested that compared to either TB patients or healthy controls, the absolute frequencies of CD3+, CD4+, CD8+, Natural killer T cell and CD4+CD25high T cell increased in co-infected patients." (PMID 23522098, 2013). "Co-infection with HBV may also influence the response to antiretroviral therapy, including HIV-1 RNA suppression and increase in CD4 count." (PMID 23527168, 2013). "While HCV coinfection may inhibit HIV-related apoptosis, HIV/HCV co-infected patients demonstrate slower CD4+ cell recovery on HAART, than those infected with HIV only." (PMID 24098405, 2013). "Gender, weight, HBV or HCV coinfection, baseline CD4 cell counts and viral load appeared to have no significant influence on nevirapine plasma concentrations." (PMID 23359265, 2013). "In order to estimate the contribution of TB per se to the associations between clinical parameters and CD4 cell counts, we have prospectively followed these variables in TB-patients, with and without HIV co-infection recruited in Ethiopian health centers." (PMID 24358268, 2013). "Collectively, these results suggest that inhibitory KIR2DL2 and KIR2DL3, which are alleles of the same locus, play a role in the inverse effects on PM and PM/HIV co-infection and the effect of KIR genes on PM in HIV positive women is dependent on high CD4 cell counts." (PMID 22715396, 2012).
co-infection (continued). "In addition, IFN-γ producing CD8 T cell frequencies were increased in spleens from co-infected mice and frequencies of hepatic IL-2 producing CD4 and CD8 T cells were reduced upon co-infection in comparison to those infected with M. tuberculosis only." (PMID 23110184, 2012). "We and others have shown that acute HIV co-infection hampers the beneficial HCV-specific CD4+ T-cell responses targeting non-structural proteins in DU." (PMID 22110669, 2011). "Seventeen (8.33%, median CD4+count 481 cells/mm3) individuals had no history of co-infection (3 male and 14 female), among the three affected males, one had been infected from his wife." (PMID 21396133, 2011). "In conclusion the course of H5N1 infection in this case was not notably different in the presence of HIV co-infection but it is possible that HIV co-infection and profound CD4 T cell depletion increase susceptibility to secondary infection." (PMID 20540811, 2010). "WHO guidelines on the timing of ART initiation in TB have evolved rapidly on the basis of new trials, such that universal ART initiation regardless of CD4 count is now advocated in TB-HIV co-infection." (PMID 21605474, 2010). "We hypothesize that the co-infection leads to a long-lasting augmentation of already heightened T cell activation in HIV-infected patients, followed by increased apoptosis of CD4 cells with decreased immune restoration." (PMID 20479873, 2010). "In a small study done in Uganda, the presence of co-infection with highly prevalent and endemic pathogens in patients with and without ART was associated with increased CD4+ T cell activation independent of CD4 count and viral load." (PMID 20479873, 2010). "Treatment with TPV/r, co-infection with hepatitis B and/or C, DAIDS grade >1 TE and CD4+ > 200 cells/mm3 at baseline were found to be independent risk factors for development of DAIDS Grade 3/4 TE; the hazard ratios (HR) were 2.8, 2.0, 2.1 and 1.5, respectively." (PMID 20003457, 2009). "Indeed, the proportion of CD4+ cells that were CD25+FoxP3+ was dramatically increased in patients with S. stercoralis and HTLV-1 co-infection." (PMID 19513105, 2009). "Although, peripheral HCV-specific CD4+ and CD8+ T-cell responses are somewhat weaker in HCV/HIV co-infected individuals, similar frequencies of intra-hepatic HCV-specific responses appear to be obtained in HCV versus HCV/HIV co-infection." (PMID 18941622, 2008). "In line with the EACS 2024 guidelines, ART should be initiated in all individuals with TB/HIV co-infection regardless of CD4 count, with earlier initiation (within 2 weeks) recommended for those with CD4 < 50 cells/μL, except in cases of TB meningitis where ART should be delayed by 4 weeks." (PMID 40748951, 2025). "Consequently, in the event of co-infection, monitoring ART response using the CD4+ T-cell count as a measure may prove to be an ineffective strategy." (PMID 40284988, 2025). "Potential confounders such as nutritional status and co-infections were not fully controlled, although the comparable distribution of co-infections across CD4+ categories suggests that co-infection burden was unlikely to confound the main hematologic or immunologic patterns." (PMID 41374357, 2025). "The primary aim of this study was to explore whether co-infection with T. solium, a potent immunomodulator, alters immune regulation in HIV-positive individuals, particularly by influencing cytokine profiles and CD4+ T-cell counts, in Tanzania’s southern highlands." (PMID 40046043, 2025). "We tested whether PZ703b could drive the reduction in latent HIV ex vivo in CD4+ T cells isolated from four HIV-positive female adults (with or without HCV coinfection) who were on ART." (PMID 40141414, 2025). "IFN-γ also displayed a significant negative relationship with CD4 counts, suggesting that T. solium co-infection may potentially alter immune regulation in HIV-positive individuals." (PMID 40046043, 2025).
co-infection (continued). "In this way, previous studies by our group have demonstrated that the number of VL episodes is inversely correlated with the CD4+ T-cell count and sjTREC level in patients with VL/HIV co-infection and could be a useful immunological biomarker for disease relapse." (PMID 40145085, 2025). "Because severely ill patients preferentially developed higher frequencies of co-infection with β-CCC species and higher frequencies of pre-existing β-CCCs/SARS-CoV-2 cross-reactive memory CD4+ and CD8+ T cells, T-cell exhaustion may be related to prior exposure to seasonal β-species of CCCs." (PMID 38605956, 2024). "Moreover, we found that IL-6 and TNF-α, generally induced by LPS, may promote BTLA expression on CD4+ T cells via the STAT3 and NF-κB signaling, which explains why HBV-ACLF patients with coinfection have elevated BTLA levels." (PMID 38418488, 2024). "These novel findings suggest that HLA-E/Mtb restricted CD4+ and CD8+ T cells can be induced by Mtb infection but poorly upon BCG vaccination and encouraged us to elucidate the phenotype of HLA-E restricted T cells in humans with various stages of TB, including upon HIV co-infection." (PMID 39790998, 2024). "Thus, further studies to characterize CD4+ T cell recovery among PLHIV with or without TB co-infection are urgently needed." (PMID 38699317, 2024). "Moreover, in PWH and CMV coinfection, in vitro stimulation of PBMCs with CMVpp65 in the presence of IL-27 stimulation led to increased IFNγ secretion by CMVpp65-specific CD4 T cells in both CMV+PWH and CMV+PWOH (People Without HIV)." (PMID 38966644, 2024). "Hence, the baseline CD4+ T cell count at the onset of treatment serves as a reliable predictor of immunological reconstitution in HIV-infected children with or without TB co-infection." (PMID 38699317, 2024). "Furthermore, the setting of co-infection poses additional concerns, particularly regarding T-cell immunity, since with the intersecting of SARS-CoV-2, HIV and TB epidemics, SARS-CoV-2-specific CD4+ T cells have shown a lower polyfunctional capacity." (PMID 37766251, 2023). "HIV/syphilis co-infection had a negative impact on CD4 + T cell counts and HIV-RNA levels." (PMID 38288435, 2023). "In fact, due to the absence of authoritative uniform guidelines for diagnosing TBU and false-negative results caused by the low CD4+ T cell count, the number of HIV and TB co-infection cases might be underestimated." (PMID 36851658, 2023). "However, the effect of HCV co‐infection on reduced CD4 count is transient, and HCV serostatus does not affect HIV disease progression." (PMID 37221951, 2023). "Advanced age, high CD4 cell count, and positive HBeAg at baseline could be regarded as potential predictors and biological markers for HBsAg clearance in patients with HIV/HBV coinfection." (PMID 36844414, 2023). "Nevertheless, in these studies, a low rate of response to vaccination could be correlated with various risk predictors of poor response, including viral load and absolute CD4+ T-cell count, CD4/CD8 ratio, co-infection with HCV, poor general health and occult hepatitis B." (PMID 37766251, 2023). "The higher percentages of missing data on HBV and HCV co‐infections in individuals without an available CD4 count could have influenced the impact of hepatitis co‐infections on late HIV diagnosis." (PMID 37221951, 2023). "Thus, there may be a vicious circle among these factors, severe co-infection, multiple, persistent, and disseminated infections, AIGA titer, and CD4 + T cells level." (PMID 35641599, 2022). "A Generalized Linear Model (GLM) analysis confirmed this lack of association between HIV-DNA level and presence of HCV coinfection after adjusting by potential confounding variables (time since HIV diagnosis, time on cART and CD4 counts) (p = 0.095, data not shown)." (PMID 35332180, 2022).